KCNMB2 (potassium calcium-activated channel subfamily M regulatory beta subunit 2)
Description:
Regulatory subunit of the calcium activated potassium KCNMA1 (maxiK) channel. Modulates the calcium sensitivity and gating kinetics of KCNMA1, thereby contributing to KCNMA1 channel diversity. Acts as a negative regulator that confers rapid and complete inactivation of KCNMA1 channel complex. May participate in KCNMA1 inactivation in chromaffin cells of the adrenal gland or in hippocampal CA1 neurons.
Tractability: Antibody: its Gene Ontology location is reachable by antibodies, with high confidence; UniProt predicts a signal peptide or a membrane-spanning region. PROTAC: ubiquitination databases record sites on it.
Gene: Protein-coding gene on chromosome 3 (178,272,932 to 178,844,429, forward strand). Ensembl gene ENSG00000197584.
Subcellular location: Membrane
Pathways (Reactome):
Hemostasis: cGMP effects
Neuronal System: Ca2+ activated K+ channels
Gene Ontology:
Molecular function: calcium-activated potassium channel activity; protein binding; ion channel inhibitor activity; potassium channel regulator activity; potassium channel activity
Biological process: action potential; detection of calcium ion; neuronal action potential; potassium ion transport; regulation of vasoconstriction; potassium ion transmembrane transport
Cellular component: plasma membrane; voltage-gated potassium channel complex; membrane
Genetic constraint (gnomAD): Loss-of-function variants: 6 observed, 20.22 expected, observed/expected ratio (o/e) 0.3, 90% interval 0.16 to 0.59. The upper end of that interval is the gene's LOEUF score, 0.59, which puts it in group 2 of 6, group 1 being the genes least tolerant of losing a copy. Missense variants: 196 observed, 262.48 expected, observed/expected ratio (o/e) 0.75, 90% interval 0.66 to 0.84. Synonymous variants: 97 observed, 99.67 expected, observed/expected ratio (o/e) 0.97, 90% interval 0.82 to 1.15.
Homologues: Orthologues: chimpanzee KCNMB2 (100% identical), macaque KCNMB2 (100% identical), guinea pig KCNMB2 (98% identical), pig KCNMB2 (98% identical), dog KCNMB2 (97% identical), rabbit KCNMB2 (96% identical), rat Kcnmb2 (96% identical), mouse Kcnmb2 (95% identical), tropical clawed frog kcnmb2 (87% identical), zebrafish s100p (54% identical), zebrafish kcnmb2a (47% identical). Paralogues in human: KCNMB3 (39% identical), KCNMB1 (34% identical), KCNMB4 (27% identical).
Diseases named in the same sentence as KCNMB2 in open-access papers:
KCNMB2 is named in the same sentence as 16 diseases in open-access papers, as found by Europe PMC text mining. Sharing a sentence is not in itself a finding about the gene and the disease. The quoted sentences say what the papers report.
breast carcinoma (1 paper, 2023). "A nomogram was constructed using 7 IRGs, including GPR132, IFITM1, IL12B, IL18, IRF7, KCNMB2, and TACR1, to predict the 1-, 2-, and 3-year survival of breast cancer patients." (PMID 37304237, 2023).
Cough (1 paper, 2020). A sudden, audible expulsion of air from the lungs through a partially closed glottis, preceded by inhalation. "A GWAS on ACEi-induced cough detected an association with the calcium-activated potassium channel gene KCNMB2, while another GWAS found an association with the calcium-binding potassium channel-interacting protein gene KCNIP4." (PMID 32080354, 2020).
deafness (1 paper, 2015). An inherited or acquired condition characterized by the complete loss of the ability to hear from one or both ears. "In addition, KCNMB2 subunit interacts with KCNMA1, the α-subunit of potassium large conductance calcium-activated channel which also presents NIHL-associated polymorphisms and whose deletion produces progressive deafness." (PMID 26121033, 2015).
endometrial polyp (1 paper, 2024). A benign nodular lesion protruding above the surface of the endometrium. "Relevant critical genes were downregulated in endometrial polyps, including ACTA2, KCNMB1, KCNMB2, PPP1R12B, MYL9, and ACTG2." (PMID 38473810, 2024).
hearing loss (1 paper, 2015). "Another candidate gene, KCNMB2, is a subunit of large-conductance calcium-activated potassium channels previously reported in linkage disequilibrium with rs4603971, another SNP in suggestive association with hearing loss." (PMID 26121033, 2015). "Our results independently confirm the potential role of KCNMB2 for hearing loss susceptibility." (PMID 26121033, 2015).
lung carcinoma (1 paper, 2025). "Lung cancer studies included E3 (KCNK1), E8 (KCNK1, KCNN4), E12 (KCNH8, KCNMB2), E23 (KCNU1), E30 (KCNQ5-IT1), E35 (KCNK1), E43 (KCNK6), E49 (KCNN4), 2), E54 (KCNJ13), E63 (KCNK12), and E67 (KCNMB2)." (PMID 40867621, 2025).
memory (1 paper, 2018). The activities involved in the mental information processing system that receives (registers), modifies, stores, and retrieves informational stimuli. "AAV-based overexpression of Kcnmb2 in dorsal hippocampus improved spatial learning and memory in the Morris water maze in MD F1 animals, indicating that reduced Kcnmb2 expression is linked to MD F1-associated learning and memory impairments." (PMID 30405352, 2018).
viral infection (1 paper, 2018). "Moreover, in our study, Kcnmb2 overexpression was mediated by viral infection." (PMID 30405352, 2018).
KCNMB2 also shares sentences with these, for which no sentence is quoted: bladder cancer (1 paper); epilepsy (1); glioma (1); memory impairment (1); metabolic syndrome (1); polyp (1); schizophrenia (1); type 1 diabetes mellitus (1).